B4GALT5 (beta-1,4-galactosyltransferase 5)
Description:
Catalyzes the synthesis of lactosylceramide (LacCer) via the transfer of galactose from UDP-galactose to glucosylceramide (GlcCer). LacCer is the starting point in the biosynthesis of all gangliosides (membrane-bound glycosphingolipids) which play pivotal roles in the CNS including neuronal maturation and axonal and myelin formation (By similarity). Plays a role in the glycosylation of BMPR1A and regulation of its protein stability (By similarity). Essential for extraembryonic development during early embryogenesis (By similarity).
Synonyms: Beta4Gal-T5; b4Gal-T5; beta4GalT-V; BETA4-GALT-IV; gt-V
Tractability: Antibody: UniProt predicts a signal peptide or a membrane-spanning region. PROTAC: ubiquitination databases record sites on it.
Gene: Protein-coding gene on chromosome 20 (49,632,945 to 49,713,908, reverse strand). Ensembl gene ENSG00000158470.
Subcellular location: Golgi apparatus, Golgi stack membrane; Golgi apparatus
Subcellular location (Human Protein Atlas): Vesicles
Pathways (Reactome):
Metabolism: Glycosphingolipid biosynthesis; Keratan sulfate biosynthesis
Metabolism of proteins: N-Glycan antennae elongation; O-linked glycosylation of mucins
Gene Ontology:
Molecular function: protein binding; UDP-galactose:glucosylceramide beta-1,4-galactosyltransferase activity; galactosyltransferase activity; glycosyltransferase activity; N-acetyllactosamine synthase activity
Biological process: central nervous system myelination; central nervous system neuron axonogenesis; ganglioside biosynthetic process; glycoprotein biosynthetic process; neuron maturation; positive regulation of embryonic development; protein O-linked glycosylation via N-acetyl-galactosamine; regulation of protein stability; carbohydrate derivative biosynthetic process; carbohydrate metabolic process
Cellular component: trans-Golgi network; Golgi apparatus; Golgi membrane; Golgi cisterna membrane
Genetic constraint (gnomAD): Loss-of-function variants: 9 observed, 37.81 expected, observed/expected ratio (o/e) 0.24, 90% interval 0.14 to 0.41. The upper end of that interval is the gene's LOEUF score, 0.41, which puts it in group 1 of 6, group 1 being the genes least tolerant of losing a copy. Missense variants: 297 observed, 462.02 expected, observed/expected ratio (o/e) 0.64, 90% interval 0.58 to 0.71. Synonymous variants: 168 observed, 167.45 expected, observed/expected ratio (o/e) 1, 90% interval 0.88 to 1.14.
Homologues: Orthologues: chimpanzee B4GALT5 (99% identical), pig B4GALT5 (97% identical), dog B4GALT5 (96% identical), mouse B4galt5 (95% identical), rat B4galt5 (95% identical), macaque B4GALT5 (90% identical), rabbit B4GALT5 (88% identical), guinea pig B4GALT5 (85% identical), tropical clawed frog b4galt5 (82% identical), zebrafish b4galt6 (73% identical), Caenorhabditis elegans bre-4 (31% identical), Drosophila melanogaster beta4GalNAcTA (27% identical). Paralogues in human: B4GALT6 (71% identical), B4GALT1 (35% identical), B4GALT3 (35% identical), B4GALT2 (33% identical), B4GALT4 (30% identical), B4GALT7 (24% identical).
Diseases named in the same sentence as B4GALT5 in open-access papers:
B4GALT5 is named in the same sentence as 38 diseases in open-access papers, as found by Europe PMC text mining. Sharing a sentence is not in itself a finding about the gene and the disease. The quoted sentences say what the papers report.
breast carcinoma (6 papers, 2019 to 2025). "B4GalT5 participates in the synthesis of both N-linked oligosaccharides and various glycolipids, it involves in extraembryonic development and tumorigenesis in many kinds of tumors, such as astrocytoma, glioma, breast cancer and cervical cancer." (PMID 35410157, 2022). "In breast cancer, B4GALT5 stabilizes Frizzled-1 through glycosylation, activating Wnt/β-catenin signaling to maintain cancer stemness." (PMID 40860122, 2025). "B4GALT5 can also mediate the stemness of breast cancer and is considered to be a prognostic biomarker for breast cancer." (PMID 35071226, 2021).
glioma (6 papers, 2011 to 2024). A benign or malignant brain and spinal cord tumor that arises from glial cells (astrocytes, oligodendrocytes, ependymal cells). "It has been reported that the expression of β4GalT5 is increased in the process of glioma development." (PMID 24715095, 2014). "In addition, β-1,4-galactosyltransferase 5 (β4GalT5) is a member of the β1,4-galactosyltransferase family and is effective in galactosylating the GlcNAcβ1,6Man arm of highly branched N-glycans with glioma characteristics." (PMID 37231524, 2023). "Exogenous reagents like etoposide could regulate B4GALT5 in glioma by influencing the level of related transcription factors." (PMID 27092876, 2016). "Also, overexpression of B4GalT-5 significantly suppressed arsenic trioxide (As2O3)-induced apoptosis in glioma cells, suggesting the use of B4GalT-5 inhibitors in combination therapy for gliomas." (PMID 39728102, 2024). "β4GalT5 could effectively galactosylate the GlcNAcβ1–6 branch which is a marker of glioma." (PMID 24715095, 2014). "β4GalT5 regulates the self-renewal of glioma-initiation cells and may be a novel target in glioma." (PMID 24715095, 2014).
hepatocellular carcinoma (4 papers, 2022 to 2025). A malignant tumor that arises from hepatocytes. "The increased mRNA and protein levels of B4GALT5 are associated with poor prognosis for hepatocellular carcinoma, ovarian cancer, cervical cancer and other cancers." (PMID 37240761, 2023). "Next, we checked whether B4GALT5 expression is correlated to immune infiltration level and clinical prognosis in hepatocellular carcinoma." (PMID 35410157, 2022). "In conclusion, B4GALT5 may be a potential biomarker for prognosis of patients with hepatocellular carcinoma." (PMID 35410157, 2022). "In hepatocellular carcinoma (HCC), B4GALT5 overexpression correlates with reduced survival and enhances proliferation, migration, and invasion." (PMID 40860122, 2025).
colorectal cancer (3 papers, 2020 to 2023). A primary or metastatic malignant neoplasm that affects the colon or rectum. "In colorectal cancer, B4GALT5 was considered as a diagnosis/prognostic biomarker with huge application potential which could be detected by electrochemical immunosensor." (PMID 36611197, 2023). "Interestingly, the marked increase of LacCer and its synthase b-1,4-GalT-V (B4GALT5) expressions were demonstrated in colorectal cancer tissues." (PMID 32708181, 2020).
Insulin resistance (3 papers, 2018 to 2022). Increased resistance towards insulin, that is, diminished effectiveness of insulin in reducing blood glucose levels. "In vivo, B4GalT5 knockdown in subcutaneous adipose tissue alleviated insulin resistance and adipose tissue inflammation, and increased adipogenesis in high-fat diet (HFD)-fed mice and ob/ob mice." (PMID 29415997, 2018). "B4GalT5 knockdown in subcutaneous adipose tissue protected mice from obesity-induced insulin resistance and adipose inflammation." (PMID 29415997, 2018). "This was accompanied by attenuated activation of nuclear factor-κB p65 and JNK phosphorylation, which are reportedly involved in regulating obesity-induced inflammation and insulin resistance, in B4GalT5 downregulation mice compared with controls." (PMID 29415997, 2018). "In fact, many studies have suggested that B4GALT5 may be an inflammatory factor and a regulator of M1 infiltration, which increases inflammation and insulin resistance." (PMID 35410157, 2022). "B4GalT5 may be a regulator of inflammatory cytokines and M1 infiltration, which contribute to insulin resistance in adipose tissue." (PMID 29415997, 2018). "Downregulation of B4GalT5 expression in subcutaneous adipose tissue alleviated insulin resistance, inflammation, and improved metabolic status of high-fat diet (HFD)-induced obesity and ob/ob mice by promoting adipogenic commitment and reducing macrophage inflammation in adipose tissue." (PMID 29415997, 2018). "In addition, intraperitoneal glucose tolerance test (GTT) and insulin tolerance test (ITT) showed B4GalT5 knockdown mice were protected from obesity-induced glucose intolerance and insulin resistance." (PMID 29415997, 2018). "In mature 3T3-L1 adipocytes, TNF-α-induced insulin resistance was accompanied by a variety of changes in the sugar chain structure, including the increase in the expression of β4GalT5, suggesting that β4GalT5 might also be involved in the inflammatory response process." (PMID 29546034, 2018). "This suggests that B4GalT5 may be involved in the regulation of obesity and insulin resistance." (PMID 29415997, 2018). "Thus, B4GalT5 might be a new potential target for reducing obesity and insulin resistance." (PMID 29415997, 2018). "Then we detected B4GalT5 expression in subcutaneous adipose tissue of HFD mice and ob/ob mice, which were hyperglycemic and exhibited insulin resistance." (PMID 29415997, 2018).
myocardial hypertrophy (3 papers, 2023 to 2025). "Importantly, the inhibition of UGCG ameliorated the pathological changes associated with heart hypertrophy, and blocking B4GalT5 attenuated the hypertrophic effects of UGCG." (PMID 37658291, 2023). "In our current study, we demonstrated that UGCG and B4GalT5 were remarkably upregulated in heart hypertrophy brought on by pressure overload in vivo or PE in vitro." (PMID 37658291, 2023). "Considering the close association among ERK signaling, ROS levels, and myocardial hypertrophy, and the existence of potential links between ERK signaling, UGCG, and B4GalT5, we examined the expression of ERK and P38-related molecules." (PMID 37658291, 2023). "Our findings revealed a collaborative relationship between the two molecules, with B4GalT5 acting as a mediator for UGCG to promote myocardial hypertrophy, adding complexity to their biological roles." (PMID 37658291, 2023). "Furthermore, studies have reported that UGCG regulated cardiac hypertrophy through connection with Beta-1,4-galactosyltransferase 5 (B4GalT5) to mediate β-AR-regulated mitochondrial oxidative stress and ERK signaling pathway." (PMID 39934657, 2025). "Notably, limiting the expression of B4GalT5 impaired the capacity of UGCG to promote myocardial hypertrophy, suggesting that B4GalT5 acts as an intermediary for UGCG." (PMID 37658291, 2023). "Compared with the UGCG overexpressing group, the group that received a simultaneous administration of UGCG overexpression and B4GalT5 inhibition showed improved myocardial hypertrophy and myocardial fibrosis, along with a decreased myocardial size and inhibited expression of ANP and BNP." (PMID 37658291, 2023). "Therefore, this study aims to elucidate the mechanisms underlying the role of UGCG in pathological myocardial hypertrophy and investigate the potential joint mediation of UGCG and B4GalT5 in the regulation of cardiac hypertrophy." (PMID 37658291, 2023). "Furthermore, we investigated the expression level of B4GalT5 in pathological myocardial hypertrophy, revealing an elevated B4GalT5 expression in hypertrophied hearts and PE-stimulated hypertrophic cardiomyocytes compared with the normal group." (PMID 37658291, 2023). "Taken together, these findings strongly suggest that the involvement of UGCG and B4GalT5 in myocardial hypertrophy may be mediated through ERK signaling." (PMID 37658291, 2023). "Therefore, we speculated that UGCG and B4GalT5 formed a complex to regulate mitochondrial ROS levels and thereby modulate myocardial hypertrophy." (PMID 37658291, 2023). "Consequently, our findings suggest that the UGCG and B4GalT5 molecular axes may control ERK signaling, ultimately influencing myocardial hypertrophy." (PMID 37658291, 2023).
viral infection (3 papers, 2018 to 2023). "B4GALT5 was found to be significantly upregulated among the glycosyltransferase genes after viral infection." (PMID 29546034, 2018). "Therefore, it was speculated that, in the process of viral infection, B4GALT5 up-regulated the expression of antigen presenting molecules (MHC I, II) and adhesion molecules (LFA-1, ICAM-1) to strengthen the monitoring and presenting of the virus." (PMID 29546034, 2018). "Meanwhile, B4GALT5 up-regulated the expression of IFN-α and inflammatory factors (IL6, IL-18, IL-1β, TNF-α) to resist viral infection." (PMID 29546034, 2018).
colon cancer (2 papers, 2019 to 2023). "In our study, we identified 12 genes, among which gene B4GALT5 exhibited the highest levels of 5hmC in colon cancer cfDNA." (PMID 37628686, 2023). "Just recently, B4GALT5 has been identified as a potential novel target for the diagnosis and therapy in human CRC—increased B4GALT5 mRNA/protein expression and enzymatic activity have been observed in colon tumors, as compared with the normal colon tissue." (PMID 31801289, 2019). "However, when the expression analysis of B4GALT5 gene was performed in EpCAM+ cells isolated from the same colon tumor samples, its mRNA levels were increased significantly." (PMID 31801289, 2019).
COVID-19 (2 papers, 2023 to 2024). A disease caused by infection with severe acute respiratory syndrome coronavirus 2. "Characteristic biomarkers showed high diagnostic efficacy in distinguishing COVID-19-related IS from control samples, with an AUC of 0.984 (95% CI 0.950–1,000) for B4GALT5, 0.966 (95% CI 0.914–0.998) for CRISPLD2, and 0.991 (95% CI 0.966 to 1.000) for F5." (PMID 37606960, 2023). "Finally, three genes associated with immunity (B4GALT5, CRISPLD2, F5) and two genes associated with ferroptosis (ACSL1, CREB5) were identified up-regulated in COVID-19-related IS." (PMID 37606960, 2023). "Therefore, B4GALT5, CRISPLD2 and F5 may be potent targets for the treatment of COVID-19-associated IS." (PMID 37606960, 2023). "SRPK1, CSGALNACT2, B4GALT5, MEGF9, and KLF5 have increased mRNA expression in patients with severe COVID-19 compared with mild and non-COVID-19 patients." (PMID 38262689, 2024). "Then we screened 3 hub genes (B4GALT5, CRISPLD2, F5) which were up-regulated in both COVID-19 and IS by multiple machine learning methods combined with the mRNA expression of genes." (PMID 37606960, 2023). "We then analyzed the mRNA expression of 9 genes, and 3 genes (B4GALT5, CRISPLD2, F5) were found up-regulated in both COVID-19 and IS (p < 0.001)." (PMID 37606960, 2023). "However, the role of B4GALT5 in COVID-19 and IS was not known." (PMID 37606960, 2023).
melanoma (2 papers, 2018 to 2025). A malignant, usually aggressive tumor composed of atypical, neoplastic melanocytes. "The lactosylceramide (LacCer) synthase B4GalT5 was upregulated during malignant transformation of mouse melanoma B16-F10 cells, and reduced expression of the B4GalT5 gene significantly reduced tumorigenic and metastatic potential." (PMID 29773994, 2018). "We selected the best candidate from a battery of shRNAs for each of these genes and confirmed through viability assay that individually knocking down ST3GAL5, B4GALT5 or UGCG diminished the cytotoxicity of both AgGom and HiGom in melanoma cells." (PMID 41271646, 2025). "Therefore, we followed up by using shRNA knock-down in melanoma cells to target the hits identified from our CRISPR KO screen (ST3GAL5, B4GALT5, UGCG, p < 0.05, FDR < 0.2)." (PMID 41271646, 2025).
ovarian carcinoma (2 papers, 2023). A malignant neoplasm originating from the surface ovarian epithelium. "Moreover, we performed a knockdown assay at the cellular level to verify the function of B4GALT5 in ovarian cancer, which was upregulated in ovarian tissues and associated with poor prognosis." (PMID 36611197, 2023). "Much effort will be put into probing the intrinsic mechanism, especially in determining whether B4GALT5 regulates ovarian cancer progression through abnormal glycosylation, in our subsequent studies." (PMID 36611197, 2023).
pancreatic cancer (2 papers, 2021 to 2023). "Generally, B4GALT5 is a membrane-bound glycoprotein, and it was linked with pancreatic cancer through MUC4." (PMID 34071263, 2021). "In patients with pancreatic cancer, we discovered that increased B4GALT5 expression was substantially correlated with shorter overall survival." (PMID 37240761, 2023). "Compared to normal tissues, pancreatic cancer tissues had a considerably higher amount of B4GALT5 mRNA." (PMID 37240761, 2023). "It is proposed that MBOAT2, CDA, LPCAT2 and B4GALT5 expression may promote the onset and progression of pancreatic cancer." (PMID 37240761, 2023). "We analyzed the mRNA expression levels of the MBOAT2/CDA/LPCAT2/B4GALT5 genes in PACA patient samples and pancreatic cancer cells." (PMID 37240761, 2023). "The mRNA levels of MBOAT2, CDA, LPCAT2 and B4GALT5 were significantly higher in PACA cells than in normal human pancreatic duct epithelial cells, implying that the high expression levels of these four genes may promote the development and progression of pancreatic cancer." (PMID 37240761, 2023).
acute myeloid leukemia (1 paper, 2023). Acute myeloid leukemia (AML) is a group of neoplasms arising from precursor cells committed to the myeloid cell-line differentiation. "miR-491-5p promotes the progression of acute myeloid leukemia by regulating the expression of B4GALT5 and the PI3K/AKT signaling pathway." (PMID 37240761, 2023).
asthma (1 paper, 2025). "A genome‐wide interaction analysis of air pollution exposure and childhood asthma showed interactions with three genes, ADCY2, B4GALT5, and DLG2, which have been found to be important for the development of asthma." (PMID 40133993, 2025).
cholangiocarcinoma (1 paper, 2023). A carcinoma that arises from the intrahepatic biliary tree (intrahepatic cholangiocarcinoma) or from the junction, or adjacent to the junction, of the right and left hepatic ducts (hilar cholangiocarcinoma). "For instance, the inhibition of the glucosylceramide synthase suppresses cisplatin-induced cholangiocarcinoma apoptosis via the inhibition of the ERK signaling pathway while downregulation of B4GalT5 partially inhibits M1 macrophage-mediated adipose tissue inflammation by suppressing ERK signaling." (PMID 37658291, 2023).
diabetes (1 paper, 2018). "Here, we demonstrated that the expression of B4GalT5 was upregulated during obesity and diabetes both in human and mice." (PMID 29415997, 2018). "We showed that the expression of β1, 4-galactosyltransferase 5 (B4GalT5) was positively correlated with diabetes and obesity." (PMID 29415997, 2018).
Obesity (1 paper, 2018). Accumulation of substantial excess body fat. "Interestingly, B4GalT5 is included in a locus that has been reproducibly identified to be linked with obesity in genome-wide linkage studies." (PMID 29415997, 2018). "To explore whether downregulation of B4GalT5 affect obesity-associated metabolic status, we knocked down B4GalT5 in HFD-fed mice and ob/ob mice by injecting adenovirus carrying B4GalT5 shRNA into both sides of inguinal fat pads." (PMID 29415997, 2018). "We found for the first time that downregulation of B4GalT5 improved obesity-induced insulin sensitivity through regulating adipogenesis and M1 macrophage infiltration." (PMID 29415997, 2018). "Collectively, these studies provided new insight into the effects of B4GalT5 on the commitment of adipocytes and activation of M1 macrophages in obesity." (PMID 29415997, 2018). "To address the potential role of B4GalT5 in obesity and T2D, we first detected B4GalT5 expression in human subcutaneous adipose tissue." (PMID 29415997, 2018). "While, the expression of B4GalT5 was positively correlated to BMI, so B4GalT5 might be one of the negative regulators of adipogenesis in obesity and our results also supported the hypothesis." (PMID 29415997, 2018). "Furthermore, the high expression of B4GalT5 in obesity may be related to the infiltration of macrophages." (PMID 29415997, 2018).
ovarian tumour (1 paper, 2023). "Thus, Pearson correlation analysis between the expression level of B4GALT5 and OTU (ovarian tumour) family deubiquitinases (OTUB1, OTUB2, OTUD1, YOD1, OTUD3, OTUD4, OTUD7B) was performed." (PMID 36611197, 2023).